PSMA3 (proteasome 20S subunit alpha 3)
Description:
Component of the 20S core proteasome complex involved in the proteolytic degradation of most intracellular proteins. This complex plays numerous essential roles within the cell by associating with different regulatory particles. Associated with two 19S regulatory particles, forms the 26S proteasome and thus participates in the ATP-dependent degradation of ubiquitinated proteins. The 26S proteasome plays a key role in the maintenance of protein homeostasis by removing misfolded or damaged proteins that could impair cellular functions, and by removing proteins whose functions are no longer required. Associated with the PA200 or PA28, the 20S proteasome mediates ubiquitin-independent protein degradation. This type of proteolysis is required in several pathways including spermatogenesis (20S-PA200 complex) or generation of a subset of MHC class I-presented antigenic peptides (20S-PA28 complex). Binds to the C-terminus of CDKN1A and thereby mediates its degradation. Negatively regulates the membrane trafficking of the cell-surface thromboxane A2 receptor (TBXA2R) isoform 2.
Synonyms: HC8; PSC3
Tractability: Small molecule: an approved drug acts on it; a structure with a bound ligand is known; a high-quality ligand is known; it belongs to a druggable protein family. PROTAC: ubiquitination databases record sites on it; its protein half-life has been measured; a small molecule that binds it is known.
Gene: Protein-coding gene on chromosome 14 (58,244,740 to 58,272,012, forward strand). Ensembl gene ENSG00000100567.
Subcellular location: Cytoplasm; Nucleus
Pathways (Reactome):
Immune System: AMPK-induced ERAD and lysosome mediated degradation of PD-L1(CD274); Activation of NF-kappaB in B cells; Antigen processing: Ub, ATP-independent proteasomal degradation; Antigen processing: Ubiquitination & Proteasome degradation; CLEC7A (Dectin-1) signaling; Cross-presentation of soluble exogenous antigens (endosomes); Dectin-1 mediated noncanonical NF-kB signaling; Downstream TCR signaling; ER-Phagosome pathway; FCERI mediated NF-kB activation; GSK3B-mediated proteasomal degradation of PD-L1(CD274); Interleukin-1 signaling; NIK-->noncanonical NF-kB signaling; SPOP-mediated proteasomal degradation of PD-L1(CD274); TNFR2 non-canonical NF-kB pathway
Cell Cycle: APC/C:Cdc20 mediated degradation of Securin; APC/C:Cdh1 mediated degradation of Cdc20 and other APC/C:Cdh1 targeted proteins in late mitosis/early G1; Autodegradation of Cdh1 by Cdh1:APC/C; Autodegradation of the E3 ubiquitin ligase COP1; Cdc20:Phospho-APC/C mediated degradation of Cyclin A; FBXL7 down-regulates AURKA during mitotic entry and in early mitosis; G2/M Checkpoints; SCF(Skp2)-mediated degradation of p27/p21; SCF-beta-TrCP mediated degradation of Emi1; Separation of Sister Chromatids; The role of GTSE1 in G2/M progression after G2 checkpoint; Ubiquitin-Mediated Degradation of Phosphorylated Cdc25A; Ubiquitin-dependent degradation of Cyclin D
Signal Transduction: Asymmetric localization of PCP proteins; Degradation of AXIN; Degradation of DVL; Degradation of GLI1 by the proteasome; Degradation of GLI2 by the proteasome; Degradation of beta-catenin by the destruction complex; GLI3 is processed to GLI3R by the proteasome; Hedgehog 'on' state; Hedgehog ligand biogenesis; MAPK6/MAPK4 signaling; Negative regulation of NOTCH4 signaling; Regulation of PTEN stability and activity
and 28 more pathways
Gene Ontology:
Molecular function: protein binding; structural constituent of proteasome; ubiquitin protein ligase binding
Biological process: proteasomal protein catabolic process; proteasome-mediated ubiquitin-dependent protein catabolic process; regulation of proteasomal protein catabolic process; response to oxidative stress; apoptotic process; CD8-positive, alpha-beta T cell differentiation; CD8-positive, alpha-beta T cell homeostasis; cellular response to type I interferon; DNA damage response; DNA repair; flagellated sperm motility; immune system process; meiotic cell cycle; negative regulation of regulatory T cell differentiation; positive regulation of interleukin-2 production; positive regulation of tumor necrosis factor production; positive regulation of type II interferon production; proteasomal ubiquitin-independent protein catabolic process; regulation of G1/S transition of mitotic cell cycle; response to type II interferon; spermatogenesis; T-helper 1 cell differentiation; T-helper 17 cell differentiation; thymic T cell selection; protein catabolic process; and 1 more
Cellular component: cytoplasm; extracellular exosome; nucleus; proteasome complex; proteasome core complex; cytosol; nucleoplasm; proteasome core complex, alpha-subunit complex; proteasome storage granule; spermatoproteasome complex; synaptic vesicle
Genetic constraint (gnomAD): Loss-of-function variants: 4 observed, 22.55 expected, observed/expected ratio (o/e) 0.18, 90% interval 0.086 to 0.41. The upper end of that interval is the gene's LOEUF score, 0.41, which puts it in group 1 of 6, group 1 being the genes least tolerant of losing a copy. Missense variants: 173 observed, 242.22 expected, observed/expected ratio (o/e) 0.71, 90% interval 0.63 to 0.81. Synonymous variants: 86 observed, 79.25 expected, observed/expected ratio (o/e) 1.09, 90% interval 0.91 to 1.3.
Homologues: Orthologues: chimpanzee PSMA3 (100% identical), guinea pig PSMA3 (99% identical), mouse Psma3 (99% identical), rabbit PSMA3 (99% identical), macaque PSMA3 (95% identical), pig PSMA3 (92% identical), dog PSMA3 (89% identical), zebrafish psma3 (89% identical), rat Psma3 (87% identical), tropical clawed frog psma3 (87% identical), Drosophila melanogaster Prosalpha7 (57% identical), Caenorhabditis elegans pas-7 (49% identical). Paralogues in human: PSMA7 (32% identical), PSMA8 (31% identical), PSMA5 (30% identical), PSMA4 (29% identical), PSMA6 (29% identical), PSMA2 (28% identical), PSMA1 (26% identical), PSMB7 (18% identical), PSMB10 (15% identical), PSMB5 (13% identical), PSMB8 (13% identical), PSMB4 (13% identical), and 6 more.
Diseases named in the same sentence as PSMA3 in open-access papers:
PSMA3 is named in the same sentence as 49 diseases in open-access papers, as found by Europe PMC text mining. Sharing a sentence is not in itself a finding about the gene and the disease. The quoted sentences say what the papers report.
multiple myeloma (5 papers, 2020 to 2022). "For example, a study showed that MSCs-Exo from bone marrow contains PSMA3 and PSMA3-AS1 that can cause resistance to proteasome inhibitors when co-cultured with multiple myeloma cells." (PMID 36430452, 2022). "One study demonstrated that exosomes released by MSCs transferred their proteasome inhibitors resistance phenotype to the multiple myeloma cells, through PSMA3 and PSMA3-AS1 present in the cargo of exosome." (PMID 34993140, 2021). "We have not evaluated which mediators the EVs convey to recipient cells to transfer BZB resistance, but the proteasome subunits PSMA3 and PSMA3-S1 may transfer such resistance in vitro, and can be found in BZB-resistant myeloma patient EVs." (PMID 32903557, 2020).
breast carcinoma (4 papers, 2020 to 2025). "High-expressed PSMA family genes (e.g., PSMA2, PSMA3, PSMA4, PSMA6, and PSMA7) in breast cancer tissues are reported to be linked to a poor OS of the cancer, but higher levels of PSMA5 and PSMA8 are indicative of better clinical outcomes." (PMID 41141246, 2025). "PSMA2, PSMA3, PSMA4, PSMA6, and PSMA7 showed high expression levels, which were correlated with poor survival of breast cancer patients." (PMID 36424389, 2022). "Furthermore, PSMA2, PSMA3, PSMA4, PSMA6, and PSMA7 showed high expression levels, which were correlated with poor survival of breast cancer patients." (PMID 34943457, 2021).
gastric cancer (3 papers, 2020 to 2023). A primary or metastatic malignant neoplasm involving the stomach. "For example, exosomal PSMA3 and PSMA6 are explicitly enriched in serum during metastatic gastric cancer, but not primary gastric cancer, thus being a potential biomarker for gastric cancer metastasis." (PMID 34109113, 2021). "PSMA3 and PSMA6 were found to be remarkably higher in serum sEVs of patients with metastatic gastric cancer (mGC) than in healthy controls and patients with early GC." (PMID 36674743, 2023).
Alzheimer disease (2 papers, 2019 to 2023). A progressive, neurodegenerative disease characterized by loss of function and death of nerve cells in several areas of the brain leading to loss of cognitive function such as memory and language. "For instance, PSMA3 has been associated with altered proteasomal activity in Alzheimer’s disease." (PMID 38002524, 2023).
bladder cancer (2 papers, 2020 to 2022). "The lncRNA PSMA3 can upregulate PD-L1 and thus promote the progression and metastasis of bladder cancer." (PMID 35266439, 2022).
cholangiocarcinoma (2 papers, 2021 to 2022). A carcinoma that arises from the intrahepatic biliary tree (intrahepatic cholangiocarcinoma) or from the junction, or adjacent to the junction, of the right and left hepatic ducts (hilar cholangiocarcinoma). "Cancer-related reports on the relation of PSMA3 expression and malignancy are limited, including metastatic gastric cancer and cholangiocarcinoma." (PMID 34943457, 2021). "Thus, AMBP, NGAL, and PSMA3 are also promising potential biomarkers for cholangiocarcinoma." (PMID 36144640, 2022).
diabetes (2 papers, 2024 to 2025). "Novel VaD loci were associated with hypertension, diabetes, and neuron maintenance (SPRY2, FOXA2, AJAP1, and PSMA3)." (PMID 39046104, 2024).
melanoma (2 papers, 2017 to 2020). A malignant, usually aggressive tumor composed of atypical, neoplastic melanocytes. "PSMA1, PSMA3 and PSMA7 were significantly associated with survival outcomes in melanoma patients." (PMID 27966459, 2017). "With respect to melanoma, the mRNA expression levels of PSMA1, PSMA3, PSMA5 and PSMA6 were upregulated in melanoma compared with normal tissues according to Haqq's dataset." (PMID 27966459, 2017). "Moreover, we also revealed that melanoma had higher levels of PSMA1 and PSMA3-6 compared with normal tissues." (PMID 27966459, 2017).
colon cancer (1 paper, 2017). "Knock-down of PSMA3 (20S proteasomal protein), PSMD3 (19S proteasomal protein), and PSME1 (11S proteasomal protein) resulted in increased size and quantity of FoxM1 compared with control colon cancer cells (brace)." (PMID 28378765, 2017).
colorectal cancer (1 paper, 2024). A primary or metastatic malignant neoplasm that affects the colon or rectum. "Similarly to PSMA2, protease PSMA3 is found to be highly expressed and significantly hindered proliferation, migration, and invasion of tumor cells in colorectal cancer." (PMID 38732562, 2024).
Epstein-Barr virus infection (1 paper, 2017). An infection that is caused by Epstein-Barr virus. "Apart from being present in proteasome subunits, PSMD14 and PSMA3 were associated with Epstein-Barr virus infection." (PMID 28626423, 2017).
invasive lobular breast carcinoma (1 paper, 2017). An infiltrating lobular adenocarcinoma of the breast. "PSMA3 was found to be significantly elevated in invasive lobular breast carcinoma compared with normal tissues in Radvanyi's dataset." (PMID 27966459, 2017).
kidney chromophobe cell carcinoma (1 paper, 2017). "Compared with normal kidney tissue, PSMA1, PSMA3 and PSMA7 were upregulated in kidney chromophobe cell carcinoma, whereas PSMA5 was downregulated." (PMID 27966459, 2017). "For instance, the mRNA expression level of PSMA3 was elevated in kidney chromophobe cell carcinoma, but not in clear cell or papillary cell carcinoma." (PMID 27966459, 2017).
large cell lung carcinoma (1 paper, 2017). "In Yamagata's dataset analyzing large cell lung carcinoma vs. normal tissue, the mRNA expression level of PSMA3 was significantly upregulated in tumor tissues." (PMID 27966459, 2017).
leukemia (1 paper, 2025). A malignant (clonal) hematologic disorder, involving hematopoietic stem cells and characterized by the presence of primitive or atypical myeloid or lymphoid cells in the bone marrow and the blood. "While PSMA3, LRRC1, HNRNPD, and FAM98A demonstrated strong binding to HHT in vitro using purified proteins, their weaker engagement in leukemia cellular models highlights fundamental differences between simplified biochemical systems and complex physiological environments." (PMID 41472850, 2025).
lung carcinoma (1 paper, 2017). "PSMA3 was found to be uncorrelated with OS, FP or PPS for lung cancer patients." (PMID 27966459, 2017).
Obesity (1 paper, 2013). Accumulation of substantial excess body fat. "In summary, our study demonstrates an association between single nucleotide polymorphisms at the PSMA3 locus and obesity in children reporting a family history of obesity." (PMID 24455213, 2013). "On the other hand, the limits to conferring an unambiguous role for polymorphisms in the PSMA3 gene for the development of obesity are clearly evident from the results of the subject subgroup denying a family history of obesity." (PMID 24455213, 2013). "Our results clearly implicate the PSMA3 gene locus as an obesity risk factor in those Latvian children with a family history of obesity." (PMID 24455213, 2013). "Nevertheless, the results from case subgroup with family obesity history strongly implicate PSMA3 polymorphisms with childhood obesity, leaving aside for the moment the ambiguities of mechanisms and heritability that will need to be addressed in future studies." (PMID 24455213, 2013). "An SNP frequency examination of the subjects' first-degree relatives would shed some light on these discrepancies and would seem appropriate in the future in order to clarify the specific roles played by polymorphisms at the PSMA3 and PSMA6 c.-8C>G loci in the promotion of obesity." (PMID 24455213, 2013). "Our results using a Latvian population indicate that SNPs of the PSMA3 gene may well be a harbinger of obesity-related disorders in, at least, Eastern European populations as well." (PMID 24455213, 2013). "We investigated the possible association of polygenic obesity with single nucleotide polymorphisms of the PSMA6 and PSMA3 proteasomal genes, based on our hypothesis that altered proteasome expression may be an important factor that can result in obesity in children." (PMID 24455213, 2013). "Moreover, while the PSMA3 association with obesity per se was not statistically established for the entire case group, a trend in that direction was apparent." (PMID 24455213, 2013). "Since polygenic obesity is a major risk factor for T2DM and given the association between PSMA6 and T2DM, we hypothesize an association between childhood obesity and the PSMA6 gene as well as the PSMA3 proteasomal gene, which interacts with the PSMA6 gene in forming structurally linked proteasomes." (PMID 24455213, 2013). "However, a highly significant difference was observed between the subjects affirming a family history of obesity and non-obese controls in SNP frequency at the PSMA3 locus (P < 0.01)." (PMID 24455213, 2013). "The mean values of low-density lipoprotein cholesterol in the obese subjects were significantly different (P < 0.05) among the three genotypes (GG = 2.40 ± 0.16 mmol/L, GA = 2.20 ± 0.09 mmol/L, and AA = 3.31 ± 0.45 mmol/L) at the PSMA3 locus irrespective of family obesity history." (PMID 24455213, 2013).
rectal adenoma (1 paper, 2017). "Moreover, PSMA3 and PSMA4 were also upregulated in rectal adenoma compared with normal tissues from Sabates-Bellver's datasets." (PMID 27966459, 2017).
renal Wilms tumor (1 paper, 2017). "In Yusenko's dataset, the transcription levels of both PSMA3 and PSMA6 were higher in renal Wilms tumor than in normal tissues." (PMID 27966459, 2017).
cancer (11 papers, 2018 to 2025). A tumor composed of atypical neoplastic, often pleomorphic cells that invade other tissues. "From this subset, we prioritized five candidates (PSMA3, EWSR1, LRRC1, HNRNPD, and FAM98A) based on their SNR rankings, established roles in cancer pathways (e.g., proteasome function, RNA processing, and transcriptional regulation)." (PMID 41472850, 2025). "Recent studies have revealed that some proteasome-related genes, such as PSMA3 and PSMC2, can promote the progression of malignant biliary tumors and act as potential biomarkers to predict prognosis." (PMID 36386204, 2022). "In our analysis, 6 out of 18 genes (EIF4A3, RAN, PSMA3, CCNA2, POLR2D, CDC27) were scored as SL hits against RB1 in at least two human cancer cell lines screens." (PMID 33591981, 2021). "Of the 102 driver genes present in at least four networks, we found that PSMA, PSMB, and PSMD were the cancer driver genes with a crucial role in the proteasome pathway (with also RPN1/2, PSMA3/5/6/7, PSMB2/3/4/8/9, PSMD2/3/4/7/11/12/14)." (PMID 29304754, 2018). "There is currently no direct evidence that PSMA3 participates in tumor invasion and metastasis; however, some studies have suggested that the proteasome complex may play a role in cancer aggravation." (PMID 35669725, 2022).
tumor (4 papers, 2015 to 2024). "However, only PSMA1 and PSMA3 were significantly associated with poor outcomes in patients with tumor grade II." (PMID 27966459, 2017). "Within tumor tissue in the adequate iron group, and more so in tumors from the excess iron diet group, we found there was also significantly greater (p ≤ 0.05) expression of proteins involved in protein degradation (ANPEP, DPP7, ITGB1, PSMA1, PSMA2, PSMA3, and SERPINB1)." (PMID 38732562, 2024).
neurological disease (1 paper, 2016). "Some downregulated proteins such as DPYSL2, TPI1, ALDH, and UCHL1 were found to play critical roles in the neurological disease and PSMA1, PSMA3, PSMC2, PSMD11, and UCHL1 in protein homeostasis." (PMID 27857231, 2016).
PSMA3 also shares sentences with these, for which no sentence is quoted: infection (3 papers); CNS cancer (2); cognitive deficits (2); Hypertension (2); schizophrenia (2); acquired lipodystrophy (1); amnesia (1); asthenospermia (1); Cachexia (1); cervical cancer (1); COVID-19 (1); developmental delay (1); Dyskinesia (1); dyslipidemia (1); glioma (1); head and neck cancer (1); kidney renal cancer (1); liver cancer (1); lung adenocarcinoma (1); lymphoma (1); multiple lipomatosis (1); neurodegenerative disease (1); ovarian carcinoma (1); pancreatic cancer (1); psoriasis (1); varicocele (1); vitamin D deficiency (1).